GFI1 (growth factor independent 1 transcriptional repressor)
Diseases named in the same sentence as GFI1 in open-access papers (continued):
Sharing a sentence is not in itself a finding about the gene and the disease.
tumor (58 papers, 2012 to 2026). "Increased expression of GFI1 was associated with tumor stage and lymphatic metastasis (unpaired t test, P < 0.0001)." (PMID 35819844, 2022). "Supporting this idea, we found that Gfi1 re-expression reduces cell viability, inhibits cell proliferation, colony formation, and tumor growth in mice xenografts of cancer cell lines with loss of Gfi1 expression." (PMID 32630147, 2020). "Reduced expression of GFI1 was significantly associated with left sided and rectal (primary site) tumours." (PMID 30858927, 2019). "Treatment of MGflox tumor cells with 4-hydroxytamoxifen (4-OHT) to activate CreERTM caused a marked reduction in Gfi1 protein expression compared to cells treated with vehicle (DMSO)." (PMID 30659187, 2019). "Consistent with the TCGA Network study, we found reduced GFI1 expression was associated with high-grade and left-sided tumours, and reduced TNFRSF11A expression was associated with metastasis and high nodal involvement." (PMID 30858927, 2019). "attenuated the tumor-associated macrophages(TAM)-mediated gemcitabine resistance of PDAC by blocking the TGF-β1/Gfi-1 axis." (PMID 29254283, 2017). "Consistently, the decrease in the α-GalCer-induced anti-tumor activity was observed in Gfi1-deficient mice using a murine model of lung metastasis of B16 melanoma." (PMID 27284976, 2016). "In summary, our observations indicated that curcumin treatment in line with our hypothesis impeded the progression of MDS to AML and was associated with a lower tumour burden in GFI1-36N, -KD, Nup98-HOXD13-tg mice." (PMID 35008835, 2021). "Furthermore, the α-GalCer-dependent anti-tumor activity was impaired in T cell-specific Gfi1-deficient mice." (PMID 27284976, 2016). "In addition, a reduction of the α-GalCer-induced anti-tumor activity was observed in Gfi1-deficient mice." (PMID 27284976, 2016). "Moreover, it would be interesting to discover whether such changes occur in other neoplasms to which the GFI1 variant also predisposes." (PMID 39857691, 2025). "We next examined GFI1 expression in tissue sections of 242 primary NSCLCs, 37 primary SCLCs, and 10 tumor-adjacent normal lung tissues using IHC." (PMID 35819844, 2022). "GFI1 elevated the numbers of circulating and lung-infiltrating tumor cells in xenograft models and predicted poor prognosis of patients with lung cancer." (PMID 35819844, 2022). "In the correlation of tumor-infiltrating lymphocytes (TILs) with DEGs, we found that CLC and GFI1 were significantly associated with immune cells." (PMID 36188575, 2022). "Quantification of staining based on the intensity of GFI1 nuclear staining and the percentage of GFI1-positive tumor cells revealed higher expression of GFI1 in SCLCs than in NSCLCs, which matched the GFI1 expression pattern detected in the cell lines." (PMID 35819844, 2022). "On the other hand, inactivation of Ezh2 accelerates tumor initiation in a mouse model of Group 3 MB induced by Gfi1 and c-Myc, suggesting a different role for these players in different subset of MB26." (PMID 31996670, 2020). "The same mice were injected in both flanks with 107 MDA-MB-231 or PC3 cells transfected with Gfi1 or empty vector, and tumor growth was monitored every 3 days." (PMID 32630147, 2020). "Further studies must be done to elucidate the exact role of Gfi1 in these tumor types and their clinical implications." (PMID 32630147, 2020). "To identify other potential mechanisms by which Gfi1/Lsd1 promote tumor formation, we analyzed transcriptional profiles obtained from MG tumors (n = 7) and NSCs (n = 5)." (PMID 30659187, 2019).
tumor (continued). "Using a conditional genetic deletion approach, we show that Gfi1 is not only required for tumor initiation but is also crucial for maintaining growth of established tumors." (PMID 30659187, 2019). "Given the importance of Gfi1 in MB initiation and maintenance, we sought to further understand the mechanisms by which Gfi1 promotes tumor growth." (PMID 30659187, 2019). "We also show that Lsd1 is essential for Gfi1-mediated transformation: Gfi1 proteins that cannot recruit Lsd1 are unable to drive tumorigenesis, and genetic ablation of Lsd1 markedly impairs tumor growth in vivo." (PMID 30659187, 2019). "To gain insight into the mechanisms by which Gfi1 promotes tumor formation we performed expression profiling on MG tumor cells." (PMID 30659187, 2019). "Here, we show that Gfi1 expression is required for MB tumor maintenance and describe a critical role for the lysine demethylase Lsd1 in mediating its oncogenic effects in MB." (PMID 30659187, 2019). "In the present study, we not only demonstrate the importance of Gfi1 expression in tumor maintenance, but also show that its tumorigenic activity depends on its ability to recruit other proteins through a functional SNAG domain." (PMID 30659187, 2019). "An experimental MM mouse model was generated to investigate the effects of MM cells overexpressing Gfi1 on tumor burden and osteolysis in vivo." (PMID 30286780, 2018). "Future studies, however, will have to give us a better understanding of the repair pathways on which GFI1 expressing tumours rely for their ability to respond to, and resist, radiotherapy and chemotherapy." (PMID 31225488, 2018). "HSC and committed myeloid progenitors from Gfi‐1−/− mice show increased proliferation and are blocked myeloid differentiation, suggesting that Gfi‐1 acts as a tumor suppressor by regulating HSPC proliferation and differentiation." (PMID 29460395, 2018). "Ches1, Tcf3, Ccnc and Gfi1 are transcriptional repressors, Pten and Runx3 are tumor suppressors, and Cdkn1b is a cell cycle inhibitor." (PMID 24859236, 2014). "The differential coverage at chimeric junctions in the Gfi1 3′-UTR in tumor 359 most likely represents the expansion of distinct cellular subpopulations." (PMID 24886479, 2014). "Tumor 324 contained only a single integration at the Gfi1/Evi5 locus however it contained two integrations at the Myc/Pvt1 locus." (PMID 24886479, 2014). "While the four tumors harbored integrations in Gfi1 and ecotropic viral-integration Site 5 (Evi5) (the Gfi1/Evi5 locus), tumor 359 contained six integrations at this locus, four of which were positioned in sense in the 3′-UTR of Gfi1." (PMID 24886479, 2014). "Tumor 327 contained six interspersed integrations at the Gfi-1/Evi-5 locus, while tumor 410 contained two integrations at this locus." (PMID 24886479, 2014). "The deletion of the Gfi1 gene led to tumor regression and clearance of blast cells from blood and to the survival of the animals, whereas the appropriate control mice all died." (PMID 23528269, 2013). "The pharmacological inhibition of Lsd1 in Gfi1-driven MB in vitro and in vivo inhibits tumor cell growth and supports the idea that targeting Lsd1 may be an effective strategy for these tumors." (PMID 40556679, 2025). "However, inhibition of EZH2 in MB must be approached cautiously, as inhibition of EZH2 can lead to Gfi1 upregulation through epigenetic remodeling, promoting tumor progression in MYC-driven Group 3 MB, supporting a nuanced role for EZH2 in MB." (PMID 40556679, 2025). "Several loci that enhance Myc/Pim kinase tumor development have already been identified, including Pal-1/Gfi-1 (Growth Factor Independent 1 Transcriptional Repressor), Bmi-1 (B Lymphoma Mo-MLV Insertion Region 1 Homolog), and Runx2 (RUNX Family Transcription Factor 2)." (PMID 36694243, 2023).
tumor (continued). "Concomitantly, GFI1 reconfigured the chromatin structure of the RASGRP2 gene and increased its expression, causing Rap1 activation and subsequent sustained ERK activation upon detachment, and this led to ERK signaling dependency in tumor cells." (PMID 35819844, 2022). "Thus, GFI1 promotes tumor progression through enhancing ERK pathway, and this leads to an ERK signaling addiction in tumor cells." (PMID 35819844, 2022). "Additionally, TAMs are known to secrete TGF-β1, which results in the up-regulation of Gfi-1 expression in tumor cells." (PMID 35431936, 2022). "Different levels of GFI1 may turn it into a tumor suppressor or an oncogene in malignant myelopoiesis." (PMID 34351909, 2021). "In these tumor types, Gfi1 re-expression decreases cell proliferation, reduced colony formation density and tumor growth in nude mice xenografts, supporting the hypothesis of a tumor-suppressor role for Gfi1." (PMID 32630147, 2020). "To test whether Gfi1 hypermethylation is tumor specific or a general event in cancer, we screened a variety of cancer cell lines corresponding to different tumor types." (PMID 32630147, 2020). "Together, these data indicate that Gfi1 inhibits tumor cell growth." (PMID 32630147, 2020). "Moreover, in a previous study, we found that Gfi1 methylation predicted tumor progression despite androgen deprivation." (PMID 32630147, 2020). "We also showed that Gfi1 could have an important role regulating important cellular processes such as cell proliferation and tumor growth in these tumor types." (PMID 32630147, 2020). "Unlike the TCGA study, we did not observe an association between GFI1 and lymphatic invasion, fraction of positive lymph nodes (nodal involvement), tumour stage and distant metastasis." (PMID 30858927, 2019). "Our data suggest that Gfi1 interacts with Lsd1 and that this interaction may be important for tumor growth." (PMID 30659187, 2019). "Interestingly, the amount of Gfi1 protein detected after immunoprecipitation of Lsd1 or CoREST was similar to the amount detected after Gfi1 immunoprecipitation, suggesting that the majority of Gfi1 in the tumor cells complexes with Lsd1 and CoREST." (PMID 30659187, 2019). "Although these results indicate that Gfi1 plays a role in tumor initiation, it is unknown whether it is required for continued tumor growth." (PMID 30659187, 2019). "Based on our finding that the interaction between Gfi1 and Lsd1 is crucial for MG tumor growth, we sought to determine whether small molecule inhibitors of Lsd1 could serve as therapeutic agents for these tumors." (PMID 30659187, 2019). "Importantly, inoculation of MM cells overexpressing Gfi1 in mice induced increased bone destruction, increased osteoclast number and size, and enhanced tumor growth." (PMID 30286780, 2018). "A deeper understanding of treatment responses in these tumours will lead to both improvements in their efficacy and a reduction in their side effects and although difficult, targeting GFI1 for tumour therapy may prove to be a promising avenue in the future." (PMID 31225488, 2018). "This is consistent with a role of GFI1 in rendering leukemic cells more resistant to treatment through increased capacity of repairing DNA damage and has direct implications for the treatment of GFI1 expressing tumours." (PMID 31225488, 2018). "Decrease in MEIS1, GFI1 and cMYC, has been shown to inhibit tumour cell growth, and an increase in TRIB2 may be pro-apoptotic." (PMID 24708856, 2014).
tumor (continued). "Thus, in our systems Gfi1 silencing by hypermethylation increase AAT and ACT expression in concordance with the studies showing their association with tumorigenicity of various tumor types." (PMID 32630147, 2020). "In addition, we found that Gfi1 repress alpha 1-anti-trypsin (AAT) and alpha 1-anti-chymotrypsin (ACT) expression, two genes with important functions in cancer development, suggesting that Gfi1 silencing promotes tumor growth by increasing AAT and ACT expression in our system." (PMID 32630147, 2020). "Therefore, our observation that Lsd1 inhibitors can block growth of MG tumor cells alone and in combination with surgery and radiotherapy may have significant implications for patients with GFI1-driven MB." (PMID 30659187, 2019). "However, loss of Gfi1 did not delay tumor initiation in case of B-ALL but also impeded the ability of the B-ALL cells to grow upon transplantation." (PMID 23528269, 2013). "Co-deletion of both GFI1 and FOXO1 largely rescues NK cell differentiation, identifying a critical GFI1-FOXO1 axis required for protection against tumour metastasis." (PMID 42020400, 2026). "Treatment with 5-azadC restored GFI1 expression in DU145, LNCaP and PC-3 cells, and reduced viability and tumor growth in nude mice, confirming its tumor suppressor function." (PMID 41008642, 2025). "TAMs upregulate Gfi‐1 in tumor cells by TGF‐β secretion, which ultimately leads to reduced sensitivity of tumor cells to gemcitabine by inhibiting HMGB1 (high mobility group box 1) and CTGF (connective tissue growth factor) expression." (PMID 37994401, 2024). "Gfi-1 expression in the promoter region effectively inhibits the expression of CTGF and HMGB1, which accordingly reduce the sensitivity of tumor cells to gemcitabine." (PMID 35431936, 2022). "Moreover, they also found that the transcriptional repressor growth factor independence 1 (Gfi1) is crucial in the process of macrophage polarization, since its absence impedes macrophage polarization towards a leukaemia‐supporting state and favours an anti‐tumour state both in vitro and in vivo." (PMID 33037771, 2020). "We co-infected neural progenitors with Myc and the Gfi1-P2A mutant, transplanted them into NSG mice, and monitored animals for tumor growth." (PMID 30659187, 2019). "We observed both homogenous and heterogeneous GFI1 and TNFRSF11A mRNA expression patterns across the tumour cohort." (PMID 30858927, 2019). "To better characterise the intra-tumoural expression patterns of GFI1 and TNFRSF11A, we used RNAscope® to quantify mRNA levels across 10 whole tumour sections according to tumour cell type." (PMID 30858927, 2019). "Therefore, enforced expression of Gfi1 promotes secondary G3 MB formation mimicking the effects of the absence of Ezh2, whereas the lack of Gfi1contrasted the effects of Ezh2 inactivation, together providing at least a partial rationale for Ezh2-mediated tumor suppression." (PMID 30510924, 2018). "In summary, we uncover a TET1/GFI1/EZH2/SIN3A⊣miR-22⊣CREB-MYC signalling circuit in de novo AML, in which miR-22 functions as a pivotal anti-tumour gate-keeper, distinct from its oncogenic role reported in MDS or MDS-derived AML16." (PMID 27116251, 2016). "Of note, as for BCOR, variants in GFI1 and GSE1 were also found in single tumor samples with mutations in miRNA-processing genes (not shown)." (PMID 41291966, 2025). "However, overexpression of MYC with a GFI1 P2A mutant, which disrupts the latter’s SNAG domain, in neural progenitors prevented tumor formation in mice." (PMID 40479062, 2025). "Although we have not analyzed Gfi1 methylation prevalence in other tumor types, pooled data from cell lines and primary tumors strongly indicate that Gfi1 hypermethylation is a tumor-specific event." (PMID 32630147, 2020). "Tumor suppressor properties have been proposed for Gfi1 since its re-expression in cancer cell lines lacking Gfi1 function decreases cell proliferation." (PMID 32630147, 2020).
tumor (continued). "In contrast, mice transplanted with cells expressing Gfi1-P2A were monitored for 7 months with no signs of tumor development." (PMID 30659187, 2019). "Although our previous studies demonstrated that GFI1 proteins cooperate with MYC to initiate MB formation, their role in tumor maintenance remains unclear." (PMID 30659187, 2019). "Interestingly, all these three genes additionally exert their function as tumor suppressor genes (AHRR, GFI1, CNTNAP2)." (PMID 27493699, 2015). "Epithelial cells in tumor-adjacent lung tissues did not express GFI1." (PMID 35819844, 2022). "In contrast, the effect on MB tumor models not driven by Gfi1 was much less pronounced." (PMID 30659187, 2019). "Notably, unlike its role in lymphoid system, Gfi1 appears to function as a tumor suppressor in the myeloid system." (PMID 24023884, 2013).